NF1 (neurofibromin 1)
Diseases named in the same sentence as NF1 in open-access papers (continued):
Sharing a sentence is not in itself a finding about the gene and the disease.
neurofibromatosis type 1 (continued). "Four different inherited syndromes are associated with the development F-PNETs; patients with Multiple Endocrine Neoplasia type 1(MEN1); von Hippel Lindau Disease (VHL); von Recklinghausen disease (VRH) (neurofibromatosis 1) (NF-1) and patients with tuberous sclerosis." (PMID 37113484, 2023). "Additionally, in a model for neurofibromatosis type 1 (Nf1 R683X), ataluren was efficacious in restoring levels of full-length protein and NF1 function (suppression of RAS effectors) in cortical neurons." (PMID 37047074, 2023). "Neurofibromatosis Type 1 (NF1) is a complex monogenic disorder that affects 1 in 3000 children annually, making it one of the most common genetically inherited disorders; it results from mutations of the neurofibromin 1 (NF1) gene." (PMID 37817770, 2023). "Neurofibromatosis-1 (NF-1) is commonly known as Von Recklinghausen disease." (PMID 38013269, 2023). "Neurofibromin 1 (NF1) gene encodes a negative regulator of the Ras signal transduction pathway and a number of NF1 mutations have been linked to neurofibromatosis type 1 which is commonly associated with malignant tumors and cardiovascular or cerebrovascular complications." (PMID 36973604, 2023). "Clinical evidence reveals Neurofibromin type 1 (NF1) to be critical for regulating diverse biological functions, as humans afflicted with neurofibromatosis type 1 have behavioral manifestations including a high co-morbidity with ADHD, autism, learning impairments, and sleep disruption." (PMID 38091360, 2023). "NF1 microdeletion syndrome (MIM#613675) is a clinical condition accounting for 5–11% of NF1 patients, caused by large deletions including NF1 gene and frequently associated with a severe manifestation of neurofibromatosis type 1." (PMID 37145209, 2023). "Neurofibromatosis type 1 is an autosomal dominant disorder that affects 1 in 3000 individuals.NF-1 may dominantly involve any tissue of the body, including connective tissue, nerve tissue, and vasculature." (PMID 35414028, 2022). "In phase II clinical trials of pediatric patients, MEK inhibitors have demonstrated efficacy in pretreated, non- neurofibromatosis type 1 (NF1), recurrent optic pathway and hypothalamic low-grade gliomas, as well as BRAF-mutated or NF1- associated low grade gliomas." (PMID 35480100, 2022). "DLQI, Dermatology Life Quality Index; NF1, neurofibromatosis type 1." (PMID 35371718, 2022). "For 2 out of 8 cases, neurofibromatosis type 1 (NF1) was initially suspected, but mutational analysis of NF1 turned out to be negative." (PMID 34964038, 2022). "Neurofibromatosis (NF) is an autosomal dominant disorder with an estimated prevalence of 1 per 3000–4000 individuals.1) Neurofibromatosis type I (NF-1), its most common subtype, also known as von Recklinghausen’s disease, involves a genetic modification on the long arm of chromosome 17." (PMID 34239644, 2021). "Genomic imbalance of 17q11.2 usually encompasses NF-1 (type 1 neurofibromatosis) gene." (PMID 34470638, 2021). "The first suspicion of a causal link between these kinds of hereditary syndromes and defective RAS signaling arose when the loss of neurofibromin 1 (NF1), known to be a GAP for RAS GTPases was found in association with the development of neurofibromatosis 1, one of the most common RASopathies." (PMID 34062774, 2021). "Also known as von Recklinghausen's disease, NF1 is an autosomal dominant genetic disorder in which dysregulation of Ras protein causes tumor growth in various organs." (PMID 34941051, 2021).
neurofibromatosis type 1 (continued). "Our study also provides a structural explanation for the pathogenic mutations in SPRED1 and NF1 responsible for Legius syndrome and neurofibromatosis type 1, and it explains why SPRED1 interacts with NF1 GAP but not RASA1 GAP." (PMID 32697994, 2020). "PXA has been associated with neurofibromatosis type 1 (NF1), although it is not the classic phenotype of NF1." (PMID 32612482, 2020). "NF1 (von Recklinghausen disease) is one of the most common CPS." (PMID 33282797, 2020). "They then further analyzed clinical SMN samples and confirmed that among patients with radiation-induced breast cancer, the loss of constitutional heterozygosity (LOH) of NF1 was identified in unrelated individuals without neurofibromatosis type 1." (PMID 33061844, 2020). "In patients with type 1 neurofibromatosis associated with breast cancer, the expansion of CDK4 copy number may increase the expression of the NF1 gene and then up-regulate the expression of Her2 gene in breast cancer cells." (PMID 31358010, 2019). "CPT was previously reported to be closely related to neurofibromatosis type 1 (NF1 [OMIM: 162200])." (PMID 31533797, 2019). "They all had NF1 with more than one location showing manifested neurofibromatosis." (PMID 31533797, 2019). "• Neurofibromatosis type (NF-1) is one of the most common single gene disorders." (PMID 30187267, 2018). "Instead, here we applied an established practice common to the study of hereditary diseases, and focused specifically on correlations between mutations in regions encoding protein domains or other regions of the NF1 gene and the OPG phenotype in patients with neurofibromatosis type I." (PMID 30087692, 2018). "Approximately 85% of NETs are sporadic and the remainder occur as part of familial cancer syndromes including multiple endocrine neoplasia-type 1 (MEN1), von Hippel-Lindau disease (VHL), von Recklinghausen's disease (neurofibromatosis 1, NF1), and tuberous sclerosis (TS)." (PMID 28593056, 2017). "Other curiosities are observed, such as a high rate of somatic NF1 mutation in cutaneous melanoma, lung cancer, ovarian carcinoma and glioblastoma which are not usually associated with neurofibromatosis type 1." (PMID 28637487, 2017). "Mutations in KMT2D (MIM 147920), NF1 (MIM 162200), and ZEB2 (MIM 235730) are known to cause human monogenic Mendelian syndromes (Kabuki syndrome, neurofibromatosis type 1, and Mowat-Wilson syndrome, respectively), and cardiac malformations in these syndromes occur in 3–50% of patients." (PMID 29089047, 2017). "The large Nf1 phenotype provides a potentially powerful platform to dissect the alterations in signaling cascades, and ultimately neuronal function, that result from neurofibromatosis-1." (PMID 26896440, 2016). "Whole exome sequencing of 7 neurofibromas from a patient with Neurofibromatosis type I led to identification of second hit mutations in NF1 in 5 of 7 tumors, and median of 0 (maximum 1) non-synonymous mutations in the rest of the exome." (PMID 27494029, 2016). "NF1, also known as von Recklinghausen disease, is the most common type." (PMID 27597922, 2016). "Neurofibromatosis type 1 is a common genetic disorder, but until recently there has been a lack of data on the comprehensive mutation landscape of NF1‐associated tumors." (PMID 26432421, 2015). "Indeed, PATRR17 located within an intron of the NF1 gene contributes tosome germ-line gross chromosomal rearrangements such as deletions and translocationsresulting in neurofibromatosis type 1." (PMID 25478009, 2014). "Fifteen out of 26 patients with known NF1 status were affected by neurofibromatosis type 1." (PMID 24303016, 2013). "A genetic test for RET, Von Hippel-Lindau (VHL), Neurofibromatosis type 1 (NF1), and of the genes coding for the different subunits of the succinate dehydrogenase (hereditary paraganglioma syndromes) is suggested in familial PCC to obtain a precocious diagnosis." (PMID 24267584, 2013).
neurofibromatosis type 1 (continued). "NF-1, or von Recklinghausen's disease, was first described in 1882." (PMID 22018031, 2011). "Notably, there are studies suggesting a higher cancer incidence in approximately 5 to 10% of Neurofibromatosis type 1 patients who have a micro-deletion that includes NF1, ATAD5, and several other genes." (PMID 21901109, 2011). "It has been indicated that loss of function of the NF-1 gene results in peripheral neurofibromatosis, but no definite reasons have been cited for the high incidence of primary malignant tumors in these patients." (PMID 22018031, 2011). "Neurofibromatosis type 1 (NF1) is an autosomal dominant disorder affected by NF1 gene." (PMID 20438631, 2010). "CPT is known to accompany NF1 (neurofibromatosis type 1), also called von Recklinghausen disease." (PMID 18325091, 2008). "Application of new high-resolution genomic technologies to the Nf1 knock-out mouse model may provide new insight into the mechanisms behind the cognitive impairment in humans with Neurofibromatosis type 1." (PMID 16524466, 2006). "Th NF1 c.4340A>C (p.Gln1447Pro) variant affects a conserved residue within the GAP-related domain of neurofibromin, at a codon previously recognized as pathogenic, where other substitutions such as p.Gln1447Arg, p.Gln1447His, and p.Gln1447Ter have been described in patients with neurofibromatosis." (PMID 41300842, 2025). "An example of the first is seen in NF1, where variants (e.g. NM_001042492.3:c.-272G > C) that remove the stop codon of a native uORF, transforming it into an uoORF (as there are no alternative in-frame stop codons before the CDS), have been observed in patients with neurofibromatosis type I." (PMID 40610610, 2025). "About 5–10% of neurofibromatosis type 1 (NF1) patients exhibit large genomic germline deletions that remove the NF1 gene and its flanking regions." (PMID 38448973, 2024). "Despite his mother (1141) not being affected by NF1, according to the revised diagnostic criteria for neurofibromatosis type 1, the p.Asp176Glu substitution was predicted to be damaging by 9/20 predictors, and may have a subclinical significance." (PMID 36612057, 2022). "Complete deletion of the NF1 gene is identified in 5–10% of patients with neurofibromatosis type 1 (NF1)." (PMID 34199217, 2021). "Three diseases, namely Neurofibromatosis type 1 (OMIM 162200), Duchenne/Becker muscular dystrophies (OMIM 310200), and Methylmalonic aciduria mut type (OMIM 251000), which were caused by variants in the NF1, DMD, and MUT (MIM 609058) genes, were observed in 14 diagnosed infants (19.44%, 14/72)." (PMID 30968598, 2019). "17q11.2 microdeletions, which include the neurofibromatosis type 1 (NF1) gene region, are responsible for the NF1 microdeletion syndrome, observed in 4.2% of all NF1 patients." (PMID 31703719, 2019). "NF1 or von Recklinghausen’s disease is another autosomal dominant disorder, characterized by neurofibromas, café-au-lait spots, freckling, Lisch nodules, phaeochromocytoma and paraganglioma: 0.1 to 5.7% of patients with the NF1 gene present with solitary and benign phaeochromocytomas." (PMID 29166454, 2017). "However, after a few years of clinical and ophthalmological follow-up, the absence of typical features of Neurofibromatosis type 1 and the lack of NF1 mutation led us to reconsider the original diagnosis." (PMID 24767283, 2014). "We could demonstrate the inactivation of both copies of the NF1 gene in a typical superficial spreading melanoma of a patient with neurofibromatosis type 1 which supports a non-fortuitous association of melanoma and NF1." (PMID 16961930, 2006). "Pathogenic germline variants occur in approximately half of all NF1 cases, giving rise to Neurofibromatosis type 1 (NF1) syndrome (MIM# 162200, NF1)." (PMID 40732327, 2025).
neurofibromatosis type 1 (continued). "Here, we retrospectively investigated the spectrum of NF1 deep intronic PVs in a cohort of 8,090 unrelated individuals from the University of Alabama at Birmingham (UAB) dataset with a molecularly confirmed neurofibromatosis type 1." (PMID 37186028, 2023). "Neurofibromatosis Type 1 (NF1; OMIM 613113), formerly called von Recklinghausen disease, is a rare genetic disorder transmitted by autosomal dominant inheritance." (PMID 37686284, 2023). "Neurofibromatosis type 1 (NF1, MIM #162200), also known as Von Recklinghausen disease, is a very complex though relatively common genetic condition characterized by a heterogeneous involvement of several organ systems." (PMID 33919865, 2021). "Neurofibromatosis type 1 (NF-1, MIM 162200), also known as von Recklinghausen disease, is a progressive autosomal dominant disorder." (PMID 34988040, 2021). "To elucidate the mechanisms underlying the reduced incidence of brain tumors in children with Neurofibromatosis type 1 (NF1) and asthma, we leverage Nf1 optic pathway glioma (Nf1OPG) mice, human and mouse RNAseq data, and two different experimental asthma models." (PMID 34880260, 2021). "As with the historical classification of NF1 and NF2 as a single diagnosis (von Recklinghausen’s disease), this view was significantly supported and propagated by Harvey Cushing in his 1917 review of tumors of this region." (PMID 31161239, 2020). "In the current study, the effect of neurofibromatosis on quality of life was examined by type of NF (NF1 and NF2); six studies were conducted in neurofibromatosis type 1 and sex in neurofibromatosis type 2." (PMID 31189476, 2019). "Neurofibromatosis type 1 (NF1; OMIM 162200), also known as von Recklinghausen disease, is a progressive autosomal dominant disorder in humans, mainly characterized by café-au-lait macules (CALMs), neurofibromas, skinfold freckling, and Lisch nodules." (PMID 31886188, 2019). "Neurofibromatosis type 1 (NF1, MIM #162200), also known as von Recklinghausen disease, is one of the most common autosomal dominant disorders with multisystem involvement." (PMID 31487937, 2019). "About 30% of patients with JMML have NF1 gene inactivation, while only 10% to 14% of children with JMML have a clinical diagnosis of neurofibromatosis, type 1." (PMID 27034866, 2016). "Neurofibromatosis 1 (NF1), previously known as von Recklinghausen’s disease, is a common disease (birth incidence from 1 in 2500 to 1 in 4–5000) that mainly affects the skin and peripheral nervous system." (PMID 26514695, 2015). "NF1 (MIM# 162200), also called von Recklinghausen disease or peripheral neurofibromatosis, is one of the most common autosomal dominant disorders, with virtually 100% penetrance by adulthood." (PMID 21838856, 2011). "Schwannomas are benign peripheral nerve sheath tumors (PNSTs) arising from myelin sheaths, with schwannomatosis characterized by multiple lesions without neurofibromatosis type 1 (NF1) or type 2 (NF2) stigmata." (PMID 41970298, 2026). "Notably, specific modifier genes have been identified in different genetic contexts: RNF213, MRVI1, BMPR2, and ABCC8 in neurofibromatosis type 1, and RNF213, MRVI1, and NF1 in Down syndrome." (PMID 40508049, 2025). "The ESTAND patient with NF1 finding did not present neurofibromas and skin conditions typical of neurofibromatosis." (PMID 38654924, 2024). "Although it is not a common complication, NF1-mutated neurofibromatosis type 1 patients have an increased predisposition to develop JMML, with a 200- to 350-fold increased risk compared to their wild type NF1 counterparts." (PMID 35267643, 2022). "NF1 (OMIM#162200), also known as von Recklinghausen disease, is the most common among these disorders and shows a complete penetrance, high variable expressivity and an estimated incidence of 1 in 2500–3500 live births, independently from the ethnic group, race and sex." (PMID 33066259, 2020).
neurofibromatosis type 1 (continued). "Three studies explicitly excluded children with Neurofibromatosis Type 1, with the remaining studies providing no details of the NF1 status of their study populations." (PMID 29948767, 2018). "Whole exome sequencing was carried out on an Italian family with moyamoya-complicated neurofibromatosis type 1 to identify putative genetic modifiers independent of the NF1 locus and potentially involved in moyamoya pathogenesis." (PMID 30001348, 2018). "The NF1 protein acts as a positive regulator of cAMP/PKA signaling by stimulating adenylyl cyclase activity, and genetic or pharmacological stimulation of this pathway rescues anatomic and behavioral phenotypes in both fly and mouse models of neurofibromatosis type 1." (PMID 37185294, 2023). "As a GTPase-activating protein, Neurofibromin 1 (NF1) is a tumor suppressor that negatively regulates the RAS signaling pathway, and its abnormality leads to neurofibromatosis type 1 (NF-1) disease." (PMID 37147639, 2023). "Although rare, co-occurrence of neurofibromatosis type I and MTC or its precancerous condition C-cell hyperplasia has been documented in previous literatures, several of which have identified NF1 with or without RET germline mutations by peripheral blood DNA sequencing." (PMID 36344509, 2022). "The neurofibromatosis type I testing via NF1 gene sequencing came as negative." (PMID 27034866, 2016). "Notably, somatic changes in NF1, CDKN2A/B, and PRC2 are found in most MPNST regardless of their etiology (e.g. neurofibromatosis type 1-associated vs. sporadic vs. radiation-induced), indicating that similar molecular mechanisms impact pathogenesis in these neoplasms." (PMID 32642732, 2020). "Since the data on NF1 expression in the embryonic period are scarce, and we do not have information about the maternal genome or environment, we focused on the functional anomalies (more related to the fetal period) that are better characterized in neurofibromatosis type 1." (PMID 32858845, 2020). "Neurofibromatosis type 1 (NF1) is a disorder that has a high prevalence of ASD, and mice lacking a single NF1 allele show deficits in long-term social learning and increased activation of mitogen-activated protein (MAP) kinase pathway in neurons from BLA and PFC." (PMID 37612363, 2023). "An additional problem is that no specific code exists for NF1 in the International Classification of Diseases (ICD), so that it is not possible to distinguish it from other types of neurofibromatosis, such as neurofibromatosis type 2 (NF2)." (PMID 21439034, 2011).